STAT3 (signal transducer and activator of transcription 3)
Diseases named in the same sentence as STAT3 in open-access papers (continued):
Sharing a sentence is not in itself a finding about the gene and the disease.
tumor (continued). "Mouse B cells have been shown to promote tumour progression by promoting angiogenesis in a STAT3-dependent mechanism, although TIM-1 expression was not evaluated in this population." (PMID 35660734, 2022). "Activation of the Stat3 signaling pathway leads to the nuclear translocation of Stat3 where it binds to promoter regions of target genes such as Myc, Bcl-2, cyclin D1, VEGF, and HIF-1α, some of which have been related to cell migration and tumor invasion." (PMID 35625843, 2022). "We observed that in the absence of STAT3, IL-6 induced the activation of STAT1 and its target genes suggesting that IL-6 derived from the tumor microenvironment may activate both STAT1 and STAT3 target genes in HCC tumor cells." (PMID 35267462, 2022). "STAT3 may promote stem-like cells and the epithelial-to-mesenchymal transition (EMT) and interactions between tumor cells and the microenvironment." (PMID 35712699, 2022). "By contrast, as a tumor-suppressing lncRNA, PTCSC3 down-regulated STAT3 expression." (PMID 35372012, 2022). "Under hypoxic states, IL-6 promotes hypoxia-inducible factor 1α (HIF-1α, HIF1A) and signal transducer and activator of transcription-3 (STAT-3) transcription, which stimulates VEGF expression, blood vessel formation, and tumor growth through defective angiogenesis." (PMID 36432658, 2022). "One of the main obstacles to the development of STAT3 inhibitors is the lack of an effective targeted delivery system to improve their bioavailability and tumor targetability, failing to fully demonstrate their anti-tumor effects." (PMID 36559280, 2022). "The data herein, and supported by prior studies, demonstrate that HGFL itself does not promote macrophage migration but that HGFL-dependent alterations to the tumor cell secretome promote macrophage migration, and that these alterations are MAPK-dependent, with possible Akt/Stat3 roles." (PMID 35626096, 2022). "High nuclear expression of STAT3 protein was associated with male gender (p = 0.0002) and perihilar or distal localization (p = 0.001) in CCA but not with histology, grading, and tumor staging." (PMID 35267462, 2022). "Taken together, our study identified two STAT3 SH2 domain inhibitors, which also provide diversified biological activities and structural diversity for anti-tumor drug discovery and might be promising in the treatment of cancers with hyper-activated STAT3." (PMID 35712699, 2022). "Specifically, IL-6 is released by cells in the tumor microenvironment and increases the production and subsequent release of VEGF into the environment via the IL-6/STAT3/VEGFA pathway, promoting endothelial cell activation and the subsequent formation of tubular structures." (PMID 36555614, 2022). "STAT3 and AKT proteins are known downstream targets of EGFR as well as promoters of tumor growth." (PMID 35499593, 2022). "In addition, GSEA concluded that MS4As were involved in several tumor-related pathways, including TNF-α via NF-kB signaling, IL6/JAK/STAT3 signaling, IFN- γ response, IFN-α response, and epithelial–mesenchymal transition (EMT)." (PMID 35734424, 2022). "Here, the IL‐6/JAK/STAT3 pathway was downregulated on Day 7 (NES = −1.65, FDR = 0.003) and Day 14 (NES = −1.63, FDR = 0.003), suggesting that modulation of this pathway is partially responsible for the observed NTP effects on tumor kinetics and mouse survival." (PMID 36176603, 2022). "An increasing amount of evidence suggests that many proangiogenic factors which come from tumour cells, such as S1P, IL-6 and VEGFA, could induce the activation of STAT3 and stimulate the ECs of neighbouring blood vessels." (PMID 36068200, 2022). "Numerous studies report that STAT3 could affect autophagy through modifying the key molecular such as LC3B and then affect the progression of the tumor." (PMID 35057825, 2022). "When activated, STAT3 regulates the GBM mesenchymal transition and tumor progression." (PMID 33671112, 2021).
tumor (continued). "IL-6 is a cytokine that has been related to tumor metastasis and EMT through STAT3 signaling." (PMID 34503180, 2021). "Moreover, research has found that activated STAT3 enhances the expression of VEGFA and then promotes the growth of the tumor vasculature." (PMID 34059068, 2021). "When tested in DR5‐treated tumor cell‐jurkat cell co‐culture reporter assays, inhibition of various posttranslational PD‐L1 stability regulators such as mTOR, STAT3, CDK1, and NF‐kβ did not change PD‐L1 surface expression." (PMID 33587338, 2021). "Abnormal expression of STAT3 and STAT5 can function as pro-survival mechanism to enhance tumor survival as well as growth and hence targeting these proteins by agents such as ABZ could lead to apoptosis." (PMID 33807326, 2021). "Consistent with MAFF knockdown, we observed that inhibition of BACH1, IL11, or STAT3 did not change primary tumor growth, suggesting that their main role in cancer was not the regulation of cell proliferation in our experimental settings." (PMID 34262028, 2021). "Furthermore, M2 polarization is characterized by the expression of surface CD163 and CD204, expression of intracellular STAT-3 and the production of arginase, IL-10, and transforming growth factor beta 1 (TGF-β1), supporting tumor invasion and angiogenesis." (PMID 33917013, 2021). "Here, we will focus on how STAT3 signaling regulates CAF function, and to what extent does this play a role in ECM remodeling and mediating intercellular crosstalk within the TME to create favorable conditions for tumor progression and subsequent metastasis." (PMID 34858425, 2021). "However, in line with TCR-TMART-1 responding to tumor PD-L1, CD8+ T cells in PD-L1low patients had higher expression of STAT3 and CEBPB, which are transcription factors for immune-suppressive cell subsets." (PMID 33754038, 2021). "Overall, these findings indicate that consistent overexpression of the ALKBH5-HOXA10 loop in EOC could promote tumor growth and chemoresistance by mediating the JAK2/STAT3 signaling pathway." (PMID 34496932, 2021). "For furthermore analysis, we utilized The Cancer Genome Atlas (TCGA) public database and identified GSK3β, β-Catenin, STAT3, and CD44 oncogenes to be overexpressed in GBM tumor samples compared to adjacent normal tissue groups, and this was associated with poor cancer prognoses." (PMID 33671112, 2021). "Stat3 is a master regulator of mesenchymal transformation in GBM20 and it has been described that Stat3 can be constitutively activated in GBM cells, which facilitates tumor growth and regulates the immune microenvironment." (PMID 34376733, 2021). "As such, STAT3 blockade and TGF-β inhibition improve tumor immune surveillance by NK cells." (PMID 34025641, 2021). "Following inhibition of STAT3 signalling using 5,15-diphenyl-porphine or the anti-IL-10R neutralization antibody, we observed obvious decreases in Sp1 expression on LECs and LEC attraction of M2-polarized THP-1 macrophages and tumour cells (SiHa)." (PMID 33484377, 2021). "Finally, c-Cbl overexpression, alone or in combination with Cbl-b, can also decrease STAT3/AKT/ERK phosphorylation to down-regulate PD-L1 expression and increase anti-tumor responses." (PMID 34639141, 2021). "It is therefore not surprising that the STAT3 signaling axis has long been explored in cancer therapy owing to its roles in tumor formation, metastasis, and therapeutic failure." (PMID 33477856, 2021). "In neoplastic diseases, MDSCs are major contributors to the intra-tumoral arginase activity observed in both preclinical models and cancer patients, in which tumor-derived factors, such as PGE2, can induce Arg1 expression via STAT3 or STAT6." (PMID 34037806, 2021).
tumor (continued). "Several studies have demonstrated that the effect of Src inhibitor on STAT3 activity depends on the type of tumour cells, and that inhibition of Src was not enough to suppress STAT3 activity." (PMID 34407787, 2021). "Altogether, both STAT3 activation and STAT1 inactivation induced by MSP/RON signaling may contribute to tumor immune tolerance and lead to cancer progression." (PMID 33463063, 2021). "Consistent with previous reports describing tumor-derived EVs, immune checkpoints CD47 and CD274/PD-L1, and key regulators of myeloid differentiation (e.g., TRIB1, SOCS3, STAT3) were upregulated in EwS EV-treated cells compared to control, with TC32 EVs generally eliciting stronger effect." (PMID 34440851, 2021). "This study examines the one‐two punch of blocking Ref‐1 redox signalling along with STAT3 activation on tumour growth in the presence and absence of the TME." (PMID 33274592, 2021). "The activation of STAT3 signaling and the inhibited expression of SOCS3 may be responsible for aggressive tumor growth in DNMT3b-positive ESCC cells." (PMID 34691358, 2021). "In addition to E2F, several transcription factors with critical involvement in carcinogenesis and tumor progression control EZH2 transcription, such as MYC, NF-YA, STAT3, ETS, and ELK1." (PMID 34943970, 2021). "Thus, different from the relationship between STAT3 and STING in the tumor microenvironment, STAT3 acts as a positive regulator in STING-associated activation of NK cells during CHB infection." (PMID 34299262, 2021). "Additionally, tumor-secreted factors, including IL-6 and OSM, activate Signal Transducer and Activator of Transcription 3 (STAT3) within M-MDSCs, which, in turn, drive a mesenchymal and invasive phenotype in the tumor cells." (PMID 34830776, 2021). "Studies have shown that CD4+ T cells may activate STAT3 through CCL5 to affect the chemosensitivity of PCa, and the expression of MHC I increases the immunogenicity of PCa tumor cells." (PMID 34215720, 2021). "In addition to direct effects on tumor cells, IL-6 and JAK/STAT3 signaling can have a profound effect on tumor-infiltrating immune cells." (PMID 35155571, 2021). "Global STAT3 levels were unaffected by ALK expression, however, its activated form pSTAT3 was significantly increased upon ALK induction independent of tumor presence, suggesting an early role in the latent phase before tumor onset." (PMID 33310759, 2021). "In the tumor microenvironment, elevated IL6/JAK/STAT3 signaling could suppress antitumor immune response and promote cancer cell proliferation, survival, invasiveness and metastasis." (PMID 34944787, 2021). "It was confirmed that tumor EVs (A375SM-EVs) and miR-1246 transfection activated STAT3 in HMVECs." (PMID 34226586, 2021). "Mirroring macrophages, the IL-6 enriched in the GC-MSC-CM can stimulate the phosphorylation of STAT3 and ERK1/2 in neutrophils, promoting their recruitment and activation into a pro-tumor phenotype that would finely cooperate with GC-MSC to synergistically prompt cancer migration and angiogenesis." (PMID 34046337, 2021). "Sustained high expression of STAT3 could promote the proliferation of MDSCs and upregulate the expression of VEGF, thus promoting tumor development and angiogenesis." (PMID 33986819, 2021). "However, studies have shown that both STAT3 and STAT5 have tumour suppressor roles, reflecting their paradoxical nature." (PMID 34867402, 2021). "In H460 tumor xenograft models, the administration of SH003 or docetaxel alone diminished tumor growth, and their combination effectively killed cancer cells, with increased expression of apoptotic markers and decreased expression of p-EGFR and p-STAT3." (PMID 34445110, 2021). "The absence of RIPK3 exhibits dramatically increased tumor numbers in Apcmin/+ mice through the hyperactivation of IL-6/STAT3 signals." (PMID 33996591, 2021). "IL6 is the main inducer of the STAT3 pathway in NSCLC and promotes tumour growth." (PMID 33122847, 2021).
tumor (continued). "Moreover, GC tumor-derived GM-CSF activated neutrophils and induced neutrophil B7-H4 expression via Janus kinase (JAK)-signal transducer and activator of transcription 3 (STAT3) signaling pathway activation." (PMID 33763491, 2021). "Therefore, overexpression of VCAN-AS1 promotes tumor growth and EMT by regulating the miR-106a-5p/STAT3/HIF-1α pathway." (PMID 34365889, 2021). "The combined therapy could downregulate MCL-1 levels by suppressing the phosphorylation of STAT3; therefore, we sought to determine whether altering the expression of STAT3 in NPC cells would affect tumor cell apoptosis induced by APG-1252-M1 plus gemcitabine." (PMID 34354046, 2021). "STAT-3 promotes the transcription of factors involved in inflammation (IL-6, IL-11, and IL-1β), angiogenesis (VEGF), invasion (MMPs), and regulators of cell proliferation (cyclin D1, MYC), all of which mediate pro-tumour effects." (PMID 34944729, 2021). "CD44 in breast CSCs also played a pivotal role in the regulation of tumour cell proliferation, invasion and migration by modulating the levels of c-Src, a master regulator of the MAPK, PI3K, and STAT3 signalling pathways, via the inhibition of c-Jun and degradation by AKT/GSK-3β signalling." (PMID 34944493, 2021). "Erianin, a natural product isolated from Dendrobium chrysotoxum Lindl, downregulates the IDO-induced tumor cells angiogenesis and endothelial cell-dependent angiogenesis by targeting the JAK2/STAT3 pathway and its downstream genes, such as matrix metalloproteinases-2 and -9." (PMID 34201791, 2021). "Upon knock-down of NLRP3 in the tumor, IL-1β processing is arrested and, therefore mature IL-1β-induced IL-6/STAT3 axis is no longer being amplified." (PMID 34531850, 2021). "Moreover, siRNA-mediated STAT3 inhibition reduced the total protein levels of tumor-promoting genes Mcl1, Cyclin D1, VEGF, and Bcl-XL, suggesting that STAT3 is required for proliferation and survival in Olaparib-resistant cells." (PMID 34956861, 2021). "Overall, PDAC cells in the presence of CAF cells were more sensitive to STAT3 and Ref‐1 inhibition, with the greatest tumour reduction present in combination treatment, and no reduction in the CAFs as determined by vimentin and Masson's trichrome." (PMID 33274592, 2021). "In this regard, a reciprocal regulation between STAT3 and STAT1 in tumor cells has been discussed and that different upstream signals (IFN-β vs. oncostatin-M) or even the IFN-βs from different cells may have opposite effects in response to RT and IOs." (PMID 34830176, 2021). "Furthermore, human SRCIN1-flanking regions contain several genes involved in tumor initiation and progression, such as ERBB2 (17q12), BRCA1 (17q21), retinoic acid receptor-α (RARA; 17q21) and signal transducer and activator of transcription 3 (STAT3; 17q21)." (PMID 33079227, 2021). "STAT3 activation is implicated in therapy resistance independent of MGMT methylation and in shaping the tumor ME by promoting M2 polarization in a signaling loop of immunosuppression and immune escape." (PMID 34646780, 2021). "Moreover, the hypoxic environment of TME promotes the downregulation of STAT3 activity through a CD45 protein tyrosine phosphatase-dependent mechanism, thus favouring their differentiation to tumour-promoting TAMs." (PMID 34685679, 2021). "Multiple studies have demonstrated that the cross talk of STAT3 and SphK-S1P-S1PR pathways may play an essential role in inflammation-induced tumorigenesis and tumor progression in the intestine." (PMID 33920887, 2021).
tumor (continued). "Similarly to the in vitro findings, our in vivo results indicated that the combination of SH003 and DTX suppressed tumor growth and decreased p-EGFR (Y1068) and p-STAT3 (Y705) expression compared with the control in the NSCLC xenograft model." (PMID 34445110, 2021). "In addition, FLLL31 and FLLL32, 2 novel small-molecule STAT3 inhibitors, derived from curcumin, inhibited multiple oncogenic processes, induced apoptosis in PCC lines, and reduced tumor growth and vascularity PDA mouse xenografts." (PMID 34320467, 2021). "The PDX tumour retained positivity for Ref-1, p-STAT3 and PGP9.5 and retained lack of expression of S100 and CD56, confirming retention of key IHC markers from the original tumour." (PMID 33658640, 2021). "Two variants were found exclusively in cell 2 and not in its tumor (MMP1 and STAT3), whereas two variants were found only in the tumor from which cell 6 was derived (ERBB2 and MLH3)." (PMID 33917394, 2021). "Of note, inactivation of STAT3 in regulatory B-cells reduces IL10 and TGFβ production, and augments anti-tumor immunity by enhancing cytotoxic T-cell activity and by decreasing the number of Tregs in draining lymph nodes and tumor tissues." (PMID 34944848, 2021). "IL10 was observed to activate JAK/STAT3 signaling and induce EGFR expression, which in turn promoted IL10 expression via PI3K/nucleolin signaling to facilitate a feedforward loop that supports tumor development." (PMID 34944848, 2021). "Emerging evidence has suggested that the JAK2/STAT3 pathway participates in the regulation of angiogenesis 26, and blockade of the JAK2/STAT3 pathway could inhibit tumor growth." (PMID 33976735, 2021). "Moreover, nitidine chloride, Zanthoxylum nitidum (Roxb) DC, was found to inhibit the signal transducer as well as activator of transcription 3 (STAT3) signaling in SGC-7901 and AGS human gastric cancer cell lines, which is related to tumor angiogenesis." (PMID 34572730, 2021). "Furthermore, the in vivo experiment supporting our in vitro results showed that tumor size and weight were significantly higher in MAP2K3‐KO tumors compared with controls, while STAT3 knockdown tumors had the smallest tumors." (PMID 33660414, 2021). "Moreover, IFN-γ production was low in both normal and tumor tissue and STAT1 and STAT3 were downregulated in tumor versus normal tissue." (PMID 33846436, 2021). "We also analyzed the JAK2/STAT3 pathway and EMT markers in the tumor samples by Western blot." (PMID 34895038, 2021). "Piplartine-pretreated cells failed to initiate tumor formation and metastasis, when injected subcutaneously or intravenously respectively, whereas non-treated anoikis-resistant cells had a high STAT3 expression and developed lung metastasis." (PMID 33854965, 2021). "STAT3-enhanced activation in CRC occurs from IL-6 in the serum and the tumor microenvironment, from growth factors and growth factor receptors, tyrosine kinases (Src, Bcr-Abl), and loss-of-function mutations for the STAT3 suppressors/inhibitors (phosphatases, SOCS, PIAS)." (PMID 34440220, 2021). "In addition, previous studies have demonstrated that IL-6 together with the JAK/STAT3 signaling pathway in the TME participate in processes that strongly suppress immune effector cell function and facilitate tumor progression induced by CAFs." (PMID 34635121, 2021). "Our results showed that only PS-acet.-STAT3 peptide, but not the unconjugated control peptide or the vehicle, significantly reduced tumor growth after treatment." (PMID 33491667, 2021). "Tumor mouse models and cancer patient cohorts demonstrate the usefulness of the STAT3/NOTCH axis as biomarker for patient stratification, and importantly, that STAT3 inhibition is a promising treatment option for re-sensitization of CRT-refractory tumors." (PMID 33530306, 2021). "Moreover, a positive IL-6/STAT3/RTVP-1 feedback loop was shown to be responsible of increased mesenchymal transformation, invasiveness and resistance to anti-tumour treatments in glioma cells." (PMID 34361105, 2021).